STC1 (stanniocalcin 1)
Description:
Stimulates renal phosphate reabsorption, and could therefore prevent hypercalcemia.
Synonyms: STC
Tractability: Antibody: UniProt places it where antibodies can reach, with medium confidence; UniProt predicts a signal peptide or a membrane-spanning region; its Gene Ontology location is reachable by antibodies, with medium confidence. PROTAC: ubiquitination databases record sites on it.
Gene: Protein-coding gene on chromosome 8 (23,841,929 to 23,854,806, reverse strand). Ensembl gene ENSG00000159167.
Subcellular location: Secreted
Gene Ontology:
Molecular function: identical protein binding; protein binding; hormone activity
Biological process: bone development; chondrocyte proliferation; endothelial cell morphogenesis; growth plate cartilage axis specification; intracellular calcium ion homeostasis; negative regulation of calcium ion transport; negative regulation of cell migration; negative regulation of endothelial cell migration; negative regulation of renal phosphate excretion; positive regulation of calcium ion import; regulation of cardiac muscle cell contraction; regulation of monoatomic anion transport; cellular response to cAMP; cellular response to glucocorticoid stimulus; cellular response to hypoxia; decidualization; embryo implantation; ossification; response to vitamin D; signal transduction
Cellular component: cytoplasm; nucleus; apical plasma membrane; extracellular region
Genetic constraint (gnomAD): Loss-of-function variants: 7 observed, 23.58 expected, observed/expected ratio (o/e) 0.3, 90% interval 0.17 to 0.56. The upper end of that interval is the gene's LOEUF score, 0.56, which puts it in group 2 of 6, group 1 being the genes least tolerant of losing a copy. Missense variants: 224 observed, 328.2 expected, observed/expected ratio (o/e) 0.68, 90% interval 0.61 to 0.76. Synonymous variants: 113 observed, 127.13 expected, observed/expected ratio (o/e) 0.89, 90% interval 0.76 to 1.04.
Homologues: Orthologues: chimpanzee STC1 (100% identical), macaque STC1 (99% identical), dog STC1 (98% identical), mouse Stc1 (96% identical), rat Stc1 (96% identical), pig STC1 (94% identical), guinea pig STC1 (88% identical), rabbit STC1 (83% identical), tropical clawed frog stc1 (65% identical), zebrafish stc1 (58% identical), zebrafish stc1l (51% identical), Caenorhabditis elegans W01A8.8 (13% identical). Paralogues in human: STC2 (30% identical).
Diseases named in the same sentence as STC1 in open-access papers:
STC1 is named in the same sentence as 166 diseases in open-access papers, as found by Europe PMC text mining. Sharing a sentence is not in itself a finding about the gene and the disease. The quoted sentences say what the papers report.
breast carcinoma (49 papers, 2004 to 2025). "One study linked the STC1 glycoprotein to breast cancer metastases via the EGFR pathway and the downstream MAPK/ERK signaling, which ultimately contributes to cell cycle progression." (PMID 41409683, 2025). "STC1 is a protein-coding gene associated with diseases including colon and breast cancers, it can enhance the metastasis potential of HCC through the JNK signaling pathway, and it reduces the immune function of macrophages." (PMID 38255198, 2024). "STAT3 induces the secretion of STC1 from tumor-associated fibroblasts to foster breast cancer growth." (PMID 37400459, 2023). "Mounting researches indicated that the higher expression of STC1 was associated with OC, breast cancer, and hepatocellular carcinoma." (PMID 35273656, 2022). "It has been reported that STC1 is associated with a variety of tumors, such as rectal cancer, hepatocellular carcinoma, medullary thyroid carcinoma, acute leukemia, breast cancer, and ovarian cancer." (PMID 34722511, 2021). "Stanniocalcin-1 (STC1) is a secreted glycoprotein whose increasing expression is linked to poor prognosis, progression, and metastasis of a variety of tumors, such as breast cancer, ovarian cancer, and colon cancer." (PMID 33424916, 2020). "Accumulating evidence indicates that STC1 deregulation is linked to various cancers, including breast cancer, hepatocellular carcinoma (HCC), glioblastoma multiforme (GBM), pancreatic ductal adenocarcinoma, papillary thyroid carcinoma (PTC), ovarian cancer, and gastric cancer." (PMID 39201771, 2024). "Moreover, we evaluated the association of STC1 expression levels with the survival of breast cancer patients in the Kaplan–Meier Plotter database." (PMID 37400459, 2023). "Since it is still unclear whether STC‐1 can be an independent prognostic factor for breast cancer, we used COX proportional risk models in this article to predict OS, DFS, and DDFS, respectively." (PMID 36336967, 2023). "Furthermore, growing evidence indicates that elevated expression of STC-1 is associated with a poor prognosis in various cancers such as human esophageal squamous cell carcinoma, as well as colorectal, glioma, gastric, and breast cancers." (PMID 34650342, 2021). "In breast cancer, STC1 is highly associated with the hallmarks of carcinogenesis, and could be a promising target of breast cancer treatment." (PMID 33946970, 2021). "It was reported that STC1 expression was upregulated in breast cancer, colorectal cancer, bladder cancer, and ovarian cancer, and this high expression was closely associated with the poor prognosis of cancer patients." (PMID 41020346, 2025). "After that, the highly expressed DROSHA interacts with β-Catenin to transactivate stemness gene STC1 in an RNA cleavage-independent manner, promoting breast cancer stem cell (BCSC) properties and mediating BC cell proliferation." (PMID 38711100, 2024). "Our findings showed that S100A4 can mediate the effect of breast cancer cells with high STC1 expression on lung fibroblasts." (PMID 37400459, 2023). "We examined the regulatory effect of STC1 on S100A4, and found a STC1–EGFR–ERK–S100A4 signaling axis in lung metastatic breast cancer cells." (PMID 37400459, 2023). "These indicated that S100A4 mediates the functions of STC1 in breast cancer cells and tumor microenvironments." (PMID 37400459, 2023). "In the presented study, we found that STC1 promoted the aggressive properties of breast cancer cells in vitro and metastasis to the lungs in vivo, but did not affect breast cancer proliferation." (PMID 37400459, 2023). "To further verify the clinical significance of STC1 expression, we mined the expression of STC1 in breast cancer patients in the Oncomine database." (PMID 37400459, 2023). "Upregulation of the STC-1 (stanniocalcin-1) gene by CapG in cancer cells enhances breast cancer metastasis." (PMID 37454739, 2023).
breast carcinoma (continued). "It was found that the STC1 was significantly upregulated in breast cancer patients with lung metastasis as compared with those without distant metastasis." (PMID 37400459, 2023). "Increasing evidence suggests that STC1 is highly expressed in breast cancer, ovarian cancer, colorectal cancer, and other cancers." (PMID 37988196, 2023). "In the present study, we report the role of tumor-secreted STC1 in pulmonary metastasis of breast cancer by enhancing the invasiveness of cancer cells and promoting angiogenesis and lung fibroblast inflammatory changes in the metastatic microenvironment." (PMID 37400459, 2023). "Previous studies have indicated that higher STC1 expression in tumor tissues of breast cancer patients predicts poor recurrence-free and overall survival." (PMID 37400459, 2023). "STC1 upregulates the expression of S100A4 in breast cancer cells by promoting EGFR phosphorylation and ERK signaling." (PMID 37400459, 2023). "The results indicated that the high expression of STC1 in tumor samples of breast cancer patients was linked to shortened OS and DMFS of breast cancer patients." (PMID 37400459, 2023). "The results show that STC1 modifies the metastatic microenvironment through its autocrine action on breast cancer cells." (PMID 37400459, 2023). "We found a positive correlation between the expression of S100A4 and STC1 in metastatic lesions of breast cancer patients." (PMID 37400459, 2023). "Further, we subcutaneously inoculated nude mice with a mixture of MRC5 cells and MDA-MB-231 cells and found that STC1 promoted breast cancer growth in the presence of MRC5 cells." (PMID 37400459, 2023). "In studies of colorectal cancer, lung adenocarcinoma, and breast cancer, CAFs were shown to secrete STC1 to promote tumor progression." (PMID 37004088, 2023). "In conclusion, our data establish the important role of STC1 in lung metastasis of breast cancer through its action on tumor cells and tumor microenvironments." (PMID 37400459, 2023). "This is achieved through the secretion of ANGPTL4, MMP13, and STC1 by CAFs, which promotes breast cancer growth." (PMID 38273859, 2023). "As STC1 is a breast cancer cell-derived secreted protein, it is necessary to detect microenvironmental alteration of pulmonary metastases after STC1 manipulation." (PMID 37400459, 2023). "Here, we report that tumor-secreted stanniocalcin 1 (STC1) promotes the pulmonary metastasis of breast cancer by enhancing the invasiveness of tumor cells and promoting angiogenesis and lung fibroblast activation in the metastatic microenvironment." (PMID 37400459, 2023). "In this study, we present that tumor cell-derived STC1 contributes to pulmonary metastasis of breast cancer via regulation of angiogenesis and lung fibroblast inflammation in the metastatic microenvironment." (PMID 37400459, 2023). "Previous study has indicated that the JNK signaling pathway can be activated by STC1 in breast cancer cells." (PMID 37400459, 2023). "Considering that STC1 can act as a tumor-secreted protein, we investigated the impact of STC1 on the tumor microenvironment of breast cancer lung metastases." (PMID 37400459, 2023). "STC1 was a secreted protein that existed in the TME and was associated with the malignant progression of various tumors, such as breast cancer and pancreatic ductal adenocarcinoma (PDAC)." (PMID 37004088, 2023). "Relying on transcriptome sequencing screening, we found that the target of STC1 in breast cancer cells is S100A4." (PMID 37400459, 2023). "Our study supports the evidence that STC1 is a biomarker of breast cancer and promotes tumor growth and metastasis." (PMID 36685836, 2022). "Aberrant expression of STC1 had been observed in human carcinoma samples including colorectal cancer, breast cancer, lung adenocarcinoma, hepatocellular carcinoma, and thyroid carcinomas." (PMID 35607443, 2022). "On the other hand, STC1 promotes breast cancer proliferation and invasion by activating the JNK/c-Jun signaling pathway." (PMID 35927233, 2022).
breast carcinoma (continued). "The occurrence of OC and breast cancer is related to the down-regulation of STC1 after losing BRCA1 function." (PMID 35273656, 2022). "Further studies demonstrated that STC1 is differently expressed and serves as a tumor-promoting role in various types of cancers, including breast cancer, ovarian cancer, cervical cancer, and gastric cancer." (PMID 35927233, 2022). "STC1 is a glycoprotein hormone that is secreted into the extracellular matrix and has been discussed in the literature as a promising molecular marker in breast cancer." (PMID 35422018, 2022). "To investigate the effects of STC1 on the migration of breast cancer cells, we performed a migration assay using Transwell chamber plates." (PMID 34722511, 2021). "In clinical settings, the serum concentration of STC1 was higher in breast cancer patients than in healthy women, as detected by enzyme-linked immunosorbent assay (ELISA)." (PMID 34722511, 2021). "Stanniocalcin-1 (STC1) is a glycoprotein hormone whose abnormal expression has been reported to be associated with a variety of tumors, but its function in breast cancer is not well understood." (PMID 34722511, 2021). "Our clinical data showed that the serum concentration of STC1 was higher in breast cancer patients than in healthy women, as detected by ELISA." (PMID 34722511, 2021). "A similar finding was also observed in a study on breast cancer cases showing that low STC-1 expression correlated with initially aggressive tumors and early metastases, while high STC-1 expression correlated with late relapse (tumor dormancy)." (PMID 34650342, 2021). "The expression level of STC1 in breast cancer tissues was found to be significantly higher than that in adjacent tissues (p < 0.01)." (PMID 34722511, 2021). "To explore the function of STC1 in breast cancer cells, we investigated the effects of STC1 on apoptosis in breast cancer cells by using a fluorescence-based Annexin V apoptosis assay." (PMID 34722511, 2021). "Our above data indicated that STC1 is important in the proliferation and migration of breast cancer cells, indicating that STC1 can promote tumorigenesis." (PMID 34722511, 2021). "In conclusion, our findings indicate that STC1 promotes breast cancer tumorigenesis and that breast cancers with high levels of STC1 are more resistant to treatment, potentially mediated through HR promotion." (PMID 34722511, 2021). "High levels of STC1 expression are found in cancers, such as colorectal cancer, ovarian cancer and breast cancer, while the expression of STC1 in cervical cancer was found to be lower." (PMID 33946970, 2021). "STC1 is over expression in a kind of breast cancer cell line with low lung metastasis ability and can enhance the lung metastasis ability." (PMID 37287492, 2021). "All these findings indicate that STC1 promotes breast cancer tumorigenesis and that breast cancers with a high level of STC1 are more resistant to treatment, probably through homologous recombination (HR) promotion." (PMID 34722511, 2021). "For example, an interesting study showed that STC1 is a detectable molecular marker for occult breast cancer with metastasis in the blood and bone marrow." (PMID 32468698, 2020). "Another study also confirmed a significant association between high STC1 expression and worse OS (P = .025) and RFS (P = .0007) of patients with basal subtype breast cancer." (PMID 32468698, 2020). "Conversely, in T47D cells, a luminal (ER+/PR+) breast cancer line, reduction of STC1 expression reduces in vitro cell proliferation." (PMID 32468698, 2020). "This phenomenon can be explained by a proliferation‐promoting effect of STC1 on ER + breast cancer cells, which is dependent on the ER, because the STC1 gene is coexpressed with the ER." (PMID 32468698, 2020). "The biological effects caused by inhibition of CAIX reduce invasiveness and the self‐renewal capacity by blocking STC1 induction, suggesting that STC1 promotes the invasiveness of breast cancer cells." (PMID 32468698, 2020).
breast carcinoma (continued). "In basal‐type breast cancer patients, high expression of STC‐1 protein in tissues indicated poorer relapse‐free (P = .044) and overall survival (P = .0054) compared with low expression." (PMID 32468698, 2020). "Some studies have suggested the anti-apoptosis effect of STC1, such as colorectal cancer, breast cancer, glioma tumor, thyroid cancer, ovarian cancer and so on." (PMID 28545028, 2017). "We previously reported that PR SUMOylation is transcriptionally repressive at a limited number of endogenous gene loci, including HBEGF, IRS1, and STC1; all three gene products are known to contribute to breast cancer cell proliferation." (PMID 22697792, 2012). "The detection of STC-1 mRNA in BM has also been reported in breast cancer, which correlates with multiple histopathological prognostic factors, including primary tumor size, the number of positive lymph nodes and TNM stage." (PMID 22537917, 2012). "STC-1 expression levels are universally much higher in tumor tissues and cancer cell lines, such as hepatocellular, colorectal, ovarian, breast cancer and medullary thyroid cancer, than those in corresponding normal tissues." (PMID 22537917, 2012). "However, in breast cancer, the expression and prognostic value of STC1 are different in distinct subtypes." (PMID 39654892, 2024). "S100A4 knockdown diminishes stanniocalcin 1-induced lung metastasis of breast cancer." (PMID 39830522, 2024). "In breast cancer, abnormal STC1 expression is closely tied to tumor growth and metastasis." (PMID 39668832, 2024). "STC1 is a hypoxia-induced molecular target which promotes the progression of different types of cancer, including gastric cancer, colorectal cancer, breast cancer and bladder cancer." (PMID 38336764, 2024). "A study reported that S100A4 mediates the effect of STC1 on angiogenesis in breast cancer." (PMID 38962272, 2024). "S100A4 has the function of promoting angiogenesis, and our study indicated that S100A4 could mediate the pro-angiogenic function of breast cancer cells with high STC1 expression." (PMID 37400459, 2023). "Moreover, activated JNK signaling upregulates STC1 expression in breast cancer cells with lung-tropism." (PMID 37400459, 2023). "We found a phenomenon similar to the effect of STC1 on angiogenesis, that is, the effect of STC1 on the migratory movement of fibroblasts might also be mediated by breast cancer cells." (PMID 37400459, 2023). "To investigate the contribution of STC1 to pulmonary metastasis of breast cancer, we checked the STC1 expression in breast cancer cell lines with different pulmonary metastatic potential, including TNBC cell line MDA-MB-231 and its pulmonary tropism derivative LM2-4175 (LM2)." (PMID 37400459, 2023). "We found a correlation between the expressions of JUN mRNA and STC1 mRNA in the metastases of breast cancer patients, suggesting that there may be a regulatory relationship between c-Jun and STC1." (PMID 37400459, 2023). "Breast cancer cells mediate the effect of STC1 on the tumor microenvironment." (PMID 37400459, 2023). "We further determined whether S100A4 is involved in mediating the functions of STC1 in promoting the aggression of breast cancer cells, the tubule formation of HUVECs, and the chemotactic migration of lung fibroblasts." (PMID 37400459, 2023). "STC1, Stanniocalcin 1, it has been found to promote metastasis, lipid metabolism and cisplatin chemoresistance in ovarian cancer, STC1 is mainly involved in STAT3-mediated proliferation in breast cancer and STC1 expression is thought to play an important role in driving tumor immune resistance." (PMID 38033866, 2023). "We found a pro-inflammatory effect of STC1 on lung fibroblasts, and this effect might be mediated by breast cancer cells." (PMID 37400459, 2023). "The purpose of this study was to investigate the relationship between secreted STC‐1 and prognosis in patients with breast cancer (BC) and to determine whether STC‐1 could be a key prognostic factor in BC." (PMID 36336967, 2023).